PRDM6 (PR/SET domain 6)
Diseases named in the same sentence as PRDM6 in open-access papers (continued):
Sharing a sentence is not in itself a finding about the gene and the disease.
tumor (13 papers, 2018 to 2025). "We postulated that PRDM6 contributes to HNSCC tumor cell growth likely through dysregulation of immune gene expression based on our findings that PRDM6 is a HNSCC-associated TF that participates in the TF-IRG regulons identified from IRIS3 analysis." (PMID 40936897, 2025). "Overall, our results demonstrate that PRDM6 is a tumor-associated TF preferentially expressed in malignant cells of HNSCC." (PMID 40936897, 2025). "Overexpression of PRDM6 alone in iPSC-derived neuroepithelial stem cells led to tumor formation albeit with molecular characteristics resembling those of G3-MBs, highlighting the oncogenic potential of PRDM6 in a human genetic background." (PMID 40599851, 2025). "Last, we examined tumours with enhanced PRDM6 expression (subgroups VII/VIII), in which SNCAIP gene duplication leads to aberrant activation of PRDM6 by means of enhancer hijacking." (PMID 40335697, 2025). "Our study also reveals that PRDM6 suppresses immune gene expression in HNSCC tumor cells, aligning with previous findings on the immunosuppressive roles of other PRDM family members." (PMID 40936897, 2025). "Second, depletion of endogenous PRDM6 by siRNA knockdown induced the expression of anti-tumor ISGs, ISG15 and IFITM1." (PMID 40936897, 2025). "We further characterized the histone methyltransferase PRDM6 as a potential TF that governs HNSCC tumor cell intrinsic immunity." (PMID 40936897, 2025). "The spatial locations of tumour cells were determined by the expression of MYC, MYCN and PRDM6, along with other genes associated with proliferation (for example, MKI67)." (PMID 40335697, 2025). "To understand the clonal genetic events in tumour initiation, evolution and progression, we molecularly profiled a specific tumour cohort with a known amplification of MYCN or MYC or overexpression of PRDM6 (n = 16 primary, n = 4 relapses)." (PMID 40335697, 2025). "Researchers observed that PRDM6 can act as a tumor suppressor in some instances such as in breast cancer or can act as an oncogene such as in lung cancer and leukemia." (PMID 39765675, 2024). "In parallel, an overall increase in H3K9me2 erasers (KDM3B and KDM4A in basalioma, and KDM3A in the other two tumor types) and a bladder-specific decrease in the reader PRDM6 involved in K9 dimethylation were found." (PMID 37569534, 2023). "Specifically, we identified PRDM6, a histone methyltransferase, possesses the previously unknown role in promoting tumor cell proliferation by inducing IRG expression." (PMID 40936897, 2025). "Collectively, our findings suggest that PRDM6-mediated repression of anti-tumor ISGs may play a contributory role in oral tumorigenesis." (PMID 40936897, 2025). "As PRDM6 was shown to express in HNSCC tumor cells, we next determined whether PRDM6 contributes to their growth in vitro." (PMID 40936897, 2025). "We further identified that HPV E6/E7 oncoproteins upregulate PRDM6 expression in HNSCC tumor cells, which may link PRDM6 to HPV-induced oral oncogenesis." (PMID 40936897, 2025). "To summarize, our unbiased analysis of integrated HNSCC scRNA-seq datasets led to the identification of PRDM6 as a novel TF that governs the type I IFN signaling and immune gene expression and thus promotes proliferation and growth of tumor cells, while PRDM6 itself is also under control of HPV." (PMID 40936897, 2025). "Conversely, PRDM6 may contribute to tumor progression in other contexts by affecting chromatin structure and gene expression patterns that promote malignancy." (PMID 39765675, 2024). "In contrast, implantation of NES cells without PRDM6 expression (EV) did not cause tumor formation (0/15) within a year of implantation, the endpoint in our study." (PMID 38992221, 2024). "Whether the frequent structural aberrations in these tumours are due to the PRDM6 activation, or vice versa, remains to be explored in detail." (PMID 37420249, 2023).
tumor (continued). "Moreover, immunostaining for PRDM6 via detection of its V5 epitope tag showed that NES-derived tumors had maintained PRDM6 expression, suggesting that PRDM6 may function in both tumor initiation and maintenance." (PMID 38992221, 2024). "To evaluate the impact of combined PRDM6 and MYCN overexpression on tumor formation, we performed orthotopic transplantation experiments in mice." (PMID 38992221, 2024). "SMYD2, EZH2, and SUV420H2 were up‐regulated and SETD7, PRDM1, PRDM8, PRDM6, and PRDM5 were down‐regulated in tumor." (PMID 30984543, 2019). "Among them, the histone methyltransferase PRDM6 emerged as a top, previously un-investigated TF that may regulate the immune response in HNSCC tumor cells." (PMID 40936897, 2025). "Notably, we identified PRDM6, a histone methyl-transferase previously unlinked to HNSCC, as a key regulator of immune gene expression in HNSCC tumor cells, including canonical interferon-stimulated genes (ISGs) such as ISG15 and IFITM1." (PMID 40936897, 2025). "Overall, these results indicate that PRDM6 may participate in the type I IFN signaling and control the expression of antitumor ISGs in HNSCC tumor cells, thus promoting their proliferation and growth." (PMID 40936897, 2025). "We demonstrated that PRDM6 expression occurs almost exclusively in tumor cells of clinical HNSCC tissues and that PRDM6 promotes proliferation and growth of HNSCC tumor cells in vitro while suppressing expression of anti-tumor ISGs (ISG15, IFITM1) by both loss- and gain-of-function approaches." (PMID 40936897, 2025).
cancer (7 papers, 2017 to 2025). A tumor composed of atypical neoplastic, often pleomorphic cells that invade other tissues. "For example, in some cancers, PRDM6 expression is associated with favorable outcomes due to its role in silencing oncogenes and maintaining normal cellular functions." (PMID 39765675, 2024). "We validated these observations by analyzing PRDM6 expression in HNSCC cancer cell lines and tissue microarrays (TMAs)." (PMID 40936897, 2025). "Beyond the mere data mining, we experimentally verified that PRDM6 expresses in both HNSCC cancer cell lines and HNSCC clinic TMAs from multiple subjects." (PMID 40936897, 2025). "It has oncogenic potential, and blocking PRDM6 may represent a treatment option for cancers that express it." (PMID 41155227, 2025). "In cancer, PRDM6 plays a dual role that can be context-dependent." (PMID 39765675, 2024). "READ is a cancer type with frequent PRDM dysregulations, as PRDM1 upregulation and PRDM6/8/11 downregulation were all observed." (PMID 38540967, 2024). "A small number of genes specific for cancer at baseline were downregulated in APG-treated cancer patients after 3h and 24h (ACVR2B, CACNA1F, DONSON, PIH1D3, PRDM6)." (PMID 35600369, 2022). "However, the promoter methylation levels of PRDM3, PRDM4, PRDM6, PRDM11, and PRDM12 do not show significant differences across all cancer types." (PMID 39468462, 2024).
cardiovascular disease (1 paper, 2023). "Our characterization of the regulatory elements that drive the SMC-selective expression of Prdm6 should add to our understanding of DA development and the mechanisms by which cardiovascular disease–associated variations within the Prdm6 affect its expression." (PMID 36749647, 2023). "Polymorphisms within an approximately 35 kb region of the Prdm6 third intron have been associated with cardiovascular disease and blood pressure." (PMID 36749647, 2023). "The fact that noncoding polymorphisms within the Prdm6 gene were associated with both cardiovascular disease and Prdm6 expression in arteries strongly suggests that proper control of Prdm6 levels is important for normal SMC function." (PMID 36749647, 2023). "Finally, a number of GWAS have identified noncoding variants within the Prdm6 gene that are associated with multiple cardiovascular disease endpoints, including blood pressure and intracranial aneurysm." (PMID 36749647, 2023). "Finally, using several genome-wide data sets, we identified an SMC-selective enhancer within the Prdm6 third intron that exhibited allele-specific activity, providing evidence that rs17149944 may be the causal SNP for a cardiovascular disease GWAS locus identified within the human PRDM6 gene." (PMID 36749647, 2023). "Our data also provide evidence that rs17149944 is the causal SNP for the cardiovascular disease locus within the Prdm6 third intron, though it is difficult to completely rule out the involvement of other variants." (PMID 36749647, 2023).
PRDM6 also shares sentences with these, for which no sentence is quoted: amyotrophic lateral sclerosis (1 paper); atrial fibrillation (1); childhood cancer (1); CNS tumors (1); coronary artery disease (1); head and neck cancer (1); neuroblastoma (1); osteoporosis (1); placental disorder (1); uterine corpus endometrial carcinoma (1).